RPL23AP49 (ribosomal protein L23a pseudogene 49)
Synonyms: RPL23A_12_383
Gene: Transcribed processed pseudogene on chromosome 3 (75,624,686 to 75,625,153, reverse strand). Ensembl gene ENSG00000243422.
Diseases named in the same sentence as RPL23AP49 in open-access papers:
RPL23AP49 is named in the same sentence as 1 disease in open-access papers, as found by Europe PMC text mining. Sharing a sentence is not in itself a finding about the gene and the disease.
RPL23AP49 shares sentences with these, for which no sentence is quoted: pancreatic adenocarcinoma (1 paper).